PPARD (peroxisome proliferator activated receptor delta)
Diseases named in the same sentence as PPARD in open-access papers (continued):
Sharing a sentence is not in itself a finding about the gene and the disease.
Obesity (continued). "In conclusion, our results show important associations of PPARδ rs2016520 and PPARγ rs10865170 with BMI, and the observed PPAR interactions have a combined effect on obesity due to gene–gene interaction among rs2016520, rs9794, and rs10865170." (PMID 23545576, 2013). "These genes are target genes of PPARs, which have essential roles in energy homeostasis and adipogenesis, and their expression is increased by the activation and elevation of PPARα and PPARδ, resulting in anti-obesity effects." (PMID 23382926, 2013). "Activation of hypothalamic PPARα and/or PPARγ has been implicated in weight gain and obesity, potentially consistent with elevated adiposity and DIO in PPARδ KO mice." (PMID 22916190, 2012). "It has been shown that the anti-diabetic and anti-obesity effects of PPARδ activation are brought about, in part, by a decrease in fatty acid synthesis and fat storage within synthesized TAG depots and a concomitant mobilization of complex lipid fat stores." (PMID 21843327, 2011). "Recent reports have shown that PPARδ agonists attenuated obesity-related diseases such as insulin resistance, diabetes and cardiovascular diseases, and regulated inflammatory cell function, which potentiated a systemic inflammatory response." (PMID 21966476, 2011). "By the same token, PPARδ knockout (KO) mice showed reduced energy uncoupling and were prone to obesity under high-fat diet feeding." (PMID 20814441, 2010). "PPARδ activators are in development for the treatment of dyslipidemia,obesity and/or insulin resistance in patients with the metabolic syndrome.PPARδ agonists have advantageous effects in obesity prevention and modulationof lipoprotein metabolism." (PMID 19325917, 2009). "Genetic studies indicate that overexpression of constitutively active PPARδ in mouseadipose tissue reduced hyperlipidemia, steatosis, and obesity induced by eithergenetics or a high-fat diet." (PMID 18551185, 2008). "Transgenic mice with targeted activation of Ppard in adipose tissue are resistant to both high-fat diet-induced and genetically predisposed (db/db) obesity; treatment of db/db mice with the PPARD agonist GW501516 also reversed obesity." (PMID 18657264, 2008). "Increasing the level of Pparδ in white adipose tissues has been suggested as a potential strategy to treat obesity." (PMID 18523557, 2008). "Withpharmacological agonists and genetic manipulations of PPARδcoming to fruition in recent years, these expectations arestarting to be realized, and implicate PPARδ in importantaspects of obesity, energy metabolism and metabolic disease." (PMID 17389768, 2007). "Combined, these observationsindicate that enhancement of basal metabolism by PPARδ ingeneral, and in muscle in particular, are critical for systemicenergy homeostasis, and play a pivotal role in curbing obesity andits metabolic sequelae." (PMID 17389768, 2007). "Transgenic mice inwhich constitutively active PPARδ is expressed inmuscle are highly resistant to high-fat, diet-induced obesity." (PMID 17710237, 2007). "Remarkably,constitutive activity of PPARδ in muscle protected the micefrom HFD-induced adipocyte hypertrophy, obesity, and IR,demonstrating the major influence of PPARδ-induced energydissipation in muscle on systemic energy homeostasis." (PMID 17389768, 2007). "Together, these data indicate that PPARδ and its ligands comprise a key molecular switch to regulate muscle fiber specification, obesity resistance, insulin sensitivity, and, most surprisingly, physical endurance." (PMID 15328533, 2004). "In this study, we investigated whether activation of peroxisome proliferator-activated receptor delta (PPARδ), a key regulator of lipid metabolism, could counteract obesity-related metabolic disturbances." (PMID 41519472, 2026). "Cinnamic acid may target PPARδ and attenuate endothelial dysfunction and oxidative stress in diabetes and obesity through activation of the Nrf2/HO-1 and Akt/eNOS signaling pathways." (PMID 41194880, 2025).
Obesity (continued). "PPARδ, expressed in muscles and the central nervous system, plays a role in mitochondrial biogenesis, fatty acid oxidation, and energy expenditure, offering promise for addressing obesity and neurodegenerative diseases." (PMID 40926269, 2025). "In conclusion, buspirone may ameliorate the early stage of dyslipidemia, obesity, and hypertension via the pathway of PPARδ–AMPK–PGC-1α in hypertensive and obese animals." (PMID 37168052, 2023). "Further studies investigating which ligand modulates this interaction as well as the effect of these ligands on PC-TP/ PPARδ biology could shed light on the role of this complex in the pathogenesis of obesity." (PMID 37173315, 2023). "In addition, PPARδ is involved in regulating energy metabolism in liver, skeletal muscle and adipose tissue, and it is a mechanism by which PPARD gene variants lead to obesity and insulin resistance." (PMID 36051387, 2022). "The present results denoted that the synergic effects of SNPs of rs712221 on the ESR1 gene and rs2016520 on the PPARD gene might play a substantial role in obesity development via impairing dietary metabolism, although much still remains to be explored." (PMID 36297109, 2022). "Therefore, PPARD agonists have been used as drug targets for the treatment of obesity and related diseases." (PMID 36090166, 2022). "In mice, PPARD agonists alleviate obesity induced by a high-fat diet." (PMID 36714570, 2022). "Moreover, researchers have studied the role of PPARD in obesity and diabetes and its action in adipose tissue, skeletal muscle, macrophages, and atherosclerosis." (PMID 35163565, 2022). "Activation of PPARδ has been shown to induce fatty acid oxidation and reduce obesity in mice." (PMID 35585878, 2022). "In studies conducted in OLETF rats, a model of T2DM with obesity, the synthetic PPARD agonist GW0742 attenuated hepatic fat accumulation and improved insulin signaling, validating PPARD as a potential mediator of metabolic disease and a promising target for prevention and/or therapy." (PMID 35205333, 2022). "This suggests the possibility of using such synthetic PPARδ agonists as potential therapeutic agents for the treatment and/or prevention of obesity—however, due to the highly pleiotropic effect of PPARδ activation, their potential therapeutic use in humans still requires much research." (PMID 36558537, 2022). "Also, oleanolic acid operated as a ligand of PPARγ-1 or PPARδ for management of obesity or high glucose-induced metabolic abnormality in animal and cell line models." (PMID 36092543, 2022). "Together, these data suggest that miR-29a may play a role in impaired glucose uptake and obesity via downregulation of PPARδ." (PMID 34690698, 2021). "Moreover, it has been shown that β-Stigmasterol on PPARD (PDB ID: 5U3Q) had greater affinity than Cardarine used as an anti-obesity drug." (PMID 34889899, 2021). "PPARδ is a nuclear transcription factor that is ubiquitously expressed in many tissues, such as the liver, heart, colon, and skeletal muscle and ameliorates several chronic diseases, including diabetes, obesity, atherosclerosis, and cancer." (PMID 32258142, 2020). "Furthermore, transgenic PPARδ expression in adipose tissue produced lean mice that are resistant to obesity, hyperlipidemia and tissue steatosis, induced genetically or by a high fat diet." (PMID 31847097, 2019). "However, telmisartan also induces anti-fibrotic and anti-obesity effects through PPARδ-dependent pathways and enacts anti-hepatic fibrosis and anti-dyslipidemic effects through PPARα-dependent pathways." (PMID 30850637, 2019). "Increasing the levels of PPARδ in WAT is suggested as a potential strategy to treat obesity." (PMID 31346342, 2019). "PPARδ as a nuclear receptor alleviates metabolic diseases such as obesity and atherosclerosis." (PMID 30622619, 2018).
Obesity (continued). "Similarly, L-carnitine supplementation was reported to increase expression of PGC-1α and PPARδ in rodent models of unloading, and genetic and diet-induced obesity and diabetes." (PMID 29344054, 2018). "Conversely, SFA could dilute the anti-obesity effect of GTE because the activation action of GTE on PPARδ pathway in WAT was hardly observed in SFA-enriched HF diet-fed mice." (PMID 29968774, 2018). "The activation of the PPARδ pathway by ginger extract reduced diet-induced obesity and 6-Shogaol and 6-gingerol might be responsible for the impacts of the dietary ginger on PPARδ signaling." (PMID 30072899, 2018). "Another member of the PPAR family, PPARδ, is a nuclear hormone receptor that may be related to the development of chronic diseases, including diabetes, obesity, atherosclerosis, and cancer." (PMID 29855491, 2018). "Furthermore, the lowered catabolic metabolism is involved with metabolic diseases such as NAFLD and obesity, and it is well known that PPARδ activates catabolic reactions in cells." (PMID 28386270, 2017). "Despite the fact that AR exerts pro-inflammatory effects like PPARD and RXRA, it was much less associated with development of obesity and diabetes unlike PPARD and RXRA." (PMID 29065888, 2017). "In addition, PPARs (peroxisome-proliferator-activated receptors) are the nuclear hormone receptor including PPARα, PPARδ, and PPARγ, which play a critical role in regulation of obesity, cardiovascular diseases, and inflammation." (PMID 28293264, 2017). "In addition to an increased sensitivity to diet-induced obesity, we show that PPARδIEC-KO mice are unable to increase plasma HDLc levels after stimulation with the PPARδ specific agonist GW501516." (PMID 28404991, 2017). "Regarding PPARβ/δ, activation of PPARδ in skeleton muscle leads to leads to muscle fibre type transformation, from type II to type I, the same study also show that activation of PPARβ can also prevent obesity as a results of metabolism alteration." (PMID 29236749, 2017). "Interestingly, carnitine supplementation was reported to increase expression of PGC-1α and PPARδ in rodent models of unloading, and genetic and diet-induced obesity and diabetes." (PMID 23842456, 2013). "The identification of PPARs as key regulators of diverse aspects of energy homeostasis has made them attractive pharmacological targets to treat metabolic diseases such as lipid disorders (drugs targeting PPARα or -δ), T2D (drugs targeting PPARγ), and obesity (drugs targeting PPARδ)." (PMID 22745632, 2012). "Since activation of PPARδ has shown to exert beneficial effects on preventing obesity-related diseases, natural compounds that enhance the activity of PPARδ will provide a potential to develop a functional food with anti-obesity and anti-diabetic efficacies." (PMID 22479450, 2012). "PPARδ has a role as an anti-obesity target and as an anti-diabetic, and hence may target both the cause and consequences of dyslipidemia." (PMID 21843327, 2011). "Metabolomic profiling of obese versus lean humans has also recently indicated that BCAA concentrations are increased in obesity in the context of high fat consumption, which may be correlated with decreased PPARδ activity." (PMID 21843327, 2011). "Following thepublication of several high-profile studies implicating PPARδ as a potential target for obesity andassociated metabolic disorders, multiple pharmaceutical companies haveinitiated drug discovery efforts to identify specific PPARδ, PPARα/δ, PPARγ/δ, and pan PPAR modulators." (PMID 18989368, 2008). "PPARδ is emerging as a crucial nuclear receptor for the multiorgan regulationof whole body fuel turnover, with skeletal muscle as the central organ in theburning of fat and the consequent prevention or reduction of obesity." (PMID 18815630, 2008). "Recently, we and other groups reported that PPARδ agonists might form effective drugs for obesity, diabetes, and cardiovascular disease." (PMID 16197558, 2005).
Obesity (continued). "Thus, muscle fiber conversion by stimulation with the PPARδ agonist or the activated transgene has a protective role against obesity." (PMID 15328533, 2004). "Our current study uncovers PPARδ as the first transcription factor able to drive the formation of functional type I muscle fibers, whose activation entrains complex pathways both enhancing physical performance and creating a state of obesity resistance." (PMID 15328533, 2004). "Moreover, functional genomics support the concept that skeletal muscle remodeling to a ST phenotype, either through activated calcineurin or PPARδ, can protect against the development of dietary-induced insulin resistance and obesity." (PMID 15486583, 2004). "Thus, our objective was to investigate whether the onset of obesity and diabetes affects PPARδ expression in monocytic cells." (PMID 38989454, 2024). "In addition, intestinal PPARδ protects against diet-induced obesity and dyslipidemia." (PMID 36162507, 2022). "PPARδ agonists have been shown beneficial in models of metabolic disorders in primates and may thus possess therapeutic potential in hyperlipidemia, atherosclerosis, obesity, and diabetes." (PMID 35010191, 2021). "PPARδ is ubiquitously expressed in many tissues such as liver, heart, colon, and skeletal muscle, and its functions may be related to several chronic diseases, including diabetes, obesity, atherosclerosis, and cancer." (PMID 28386270, 2017). "PPARδ agonists might modulate the development ofatherosclerosis and acute coronary syndrome, not only by targeting foam cellsand lipoprotein metabolism, or protecting against obesity, butalso by promoting endothelial cell survival via 14-3-3ε." (PMID 19325917, 2009). "PPARD regulates gene expression involved in fatty acid oxidation in the liver, and the use of its agonist (GW501516) in diet-induced or genetic models of obesity stimulated fatty acid oxidation and improved hepatic steatosis." (PMID 39899669, 2025). "In vitro, PPARδ activation promotes FAO in adipocytes and myocytes supporting its anti-obesity role." (PMID 41438090, 2025). "In summary, this is the first report of a novel anti-obesity mechanism of BBR, which was achieved through the PPARδ-dependent reduction in lipid accumulation." (PMID 37511356, 2023). "In one study, ginger extract reduced diet-induced obesity in mice and increased exercise endurance capacity by increasing skeletal muscle fat catabolism; it was suggested that this effect may be mediated by the modulatory actions of 6-SG and 6-GN on the PPARδ signaling pathway." (PMID 35585878, 2022). "Thus, PPARδ might be a potential target for treating obesity-related hypertension." (PMID 31073415, 2019). "Several of these genes, like LEP, PPARA, PPARD, LPIN1, SREBP1, and ADIPOQ are described in obesity in both humans and mice." (PMID 31921306, 2019). "In conclusion, this study demonstrates that GTE can effectively suppress obesity induced by OO-based HF diet and UFA-enriched HF diet by activation of PPARδ pathway in WAT." (PMID 29968774, 2018). "Established VDR target genes such as PPARD and PPARGC1A, which are involved in protection against an adverse metabolic phenotype (obesity, insulin resistance), were positively correlated with serum 25OHD3 in this study." (PMID 28199350, 2017). "Therefore, searching natural compounds with PPARδ modulating properties and, in particular, vascular protective activity, represent a promising approach for metabolic syndrome and related vascular disorder, also in view of their advantageous effects in endothelial system and obesity prevention." (PMID 28067284, 2017). "In a metabolic syndrome rat model (SHR/NDmcr-cp) representing characteristics of hypertension and obesity, exercise normalized the activity of SDH and the mRNA expression of PPARδ and PGC-1α." (PMID 29201040, 2017).
Obesity (continued). "Thus, while both agonists alleviate the effects of T2DM by potentially decreasing the lipid load on peripheral tissue and the induction of insulin resistance by lipotoxicity, stimulation of PPARδ may also reduce obesity, thus being a potent target for the treatment of the metabolic syndrome." (PMID 21843327, 2011). "Activation and elevation of PPARα and PPARδ expression is known to increase expression of CPT1, ACO and UCP3 to elevate energy expenditure, subsequently resulting in anti-obesity actions." (PMID 21799697, 2011). "Pharmacologicalactivation of PPARδ, using GW0742, protects heart from ischemia/reperfusioninjury in male Zucker fatty rats, a rodent model of obesity and dyslipidemia." (PMID 19325917, 2009). "Thus—through functional genomics—calcineurin, calmodulin-dependent kinase, PGC-1α, and activated PPARδ form the basis of a signaling network that controls skeletal muscle fiber-type transformation and metabolic profiles that protect against insulin resistance and obesity." (PMID 15486583, 2004). "Although PPARδ especially is a potential therapeutic target for the metabolic syndrome, insulin resistance, and obesity, no PPARδ agonists with clinical potential have presently been developed." (PMID 39860288, 2025). "Importantly, these exosomes demonstrate a regulatory role in NRs such as PPARα, PPARγ, PPARδ, RORα, ERα, and ERβ, across a range of chronic diseases, including AIDS, atherosclerosis, cancer, CRS, diabetes, NASH, neurological diseases and obesity." (PMID 39327610, 2024). "From our data, we found that PPARδ, rather than PPARα or PPARγ, plays an active role in the anti-obesity effect of BBR." (PMID 37511356, 2023). "In special, the anti-obesity and weight loss effects of telmisartan (AT1R blocker) are dependent to PPARδ, also fimasartan, a novel AT1R blocker, ameliorates nonalcoholic fatty liver disease through PPARδ activation." (PMID 37168052, 2023). "Experiments on mice and non-human primates have shown that PPARδ agonists can normalize blood lipids and reduce insulin resistance and obesity." (PMID 35957821, 2022). "Furthermore, a report demonstrated that the activator of PPARA, PPARD, and PPARG is of great anti-obesity therapeutics due to the regulation of fat and gluconeogenesis." (PMID 34889899, 2021). "Likewise, the β-Stigmasterol on PPARD (PDB ID: 5U3Q) had better affinity than Cardarine, which is used as an anti-obesity drug." (PMID 34889899, 2021). "Long-term administration of telmisartan significantly reduced visceral fat and prevented high-fat diet-induced obesity in wild-type mice and hypertensive rats but not in PPARδ knockout mice." (PMID 31073415, 2019). "On the other hands, anti-obesity effect of GTE was less effective on SFA-enriched HF diet than on UFA-enriched HF diet, suggesting that SFA would attenuate the GTE effect through suppressing the PPARδ pathway activation effect of GTE." (PMID 29968774, 2018). "The SNPs of ABCA-1 (LDL-C and ApoA1/ApoB); LIPC (TC, LDL-C, ApoA1 and ApoB); LIPG (ApoB); MTHFR (TC, TG and LDL-C); MYLIP (TC and TG); PCSK9 (TG, HDL-C, ApoB and ApoA1/ApoB); PPARD (TG and ApoA1/ApoB); and SCARB1 (TG, ApoA1 and ApoB) interacted with overweight/obesity to modulate serum lipid levels." (PMID 23039238, 2012). "However, the development of a number of high affinity synthetic ligands for PPARδ has shown the receptor holds considerable promise for the treatment of T2DM, the metabolic syndrome, dyslipidemia and obesity." (PMID 21843327, 2011). "Therefore,the PPARδ agonist (GW501516) is currently in phase III clinical trials to evaluate its use for treatment of patients withhyperlipidemias and obesity." (PMID 18551185, 2008). "No PPARδ agonists have been developed with clinical potential, although it was recently reported that PPARδ is a potential therapeutic target for metabolic syndrome, insulin resistance, and obesity." (PMID 39860288, 2025).